PSEN2 (presenilin 2)
Diseases named in the same sentence as PSEN2 in open-access papers (continued):
Sharing a sentence is not in itself a finding about the gene and the disease.
Alzheimer disease (continued). "The lncRNAs within the mRNA sequences in Alzheimer's disease genes, namely, APP or AD1, APOE or AD2, PSEN1 or AD3, and PSEN2 or AD4, have been analyzed in terms of fractal dimension computation and correlation analysis." (PMID 23662159, 2013). "Missense mutations in three different genes encoding amyloid-β precursor protein (APP, [MIM 104760]), presenilin 1 (PSEN1, [MIM 104311]) and presenilin 2 (PSEN2, [MIM 600759]) are recognized to cause familial early-onset Alzheimer disease (EO-AD; [MIM 104300])." (PMID 22044463, 2011). "In Alzheimer's disease (AD), characterized by the presence of amyloid-beta (Aβ) plaques and tau protein tangles, critical genetic factors include the amyloid precursor protein (APP), presenilin 1 (PSEN1), presenilin 2 (PSEN2), and apolipoprotein E (APOE)." (PMID 39411638, 2024). "Moreover, the usage of different promoters has been described for genes involved in Alzheimer’s disease, such as apolipoprotein E gene (APOE) and the presenilin-2 gene (PSEN2)." (PMID 35203451, 2022). "PSEN2 mutations, like the one in HCM591, have been reported in association with familial Alzheimer’s disease and DCM, but not HCM, and those associated with DCM impair calcium signaling and handling." (PMID 32344918, 2020). "Our results suggest a potential benefit to screening nonfamilial Alzheimer disease (AD) cases with onset before 50 y for APP, PSEN1, and PSEN2 mutations." (PMID 28350801, 2017). "Besides, various gene mutations closely associated with mitochondrial function, including those involving amyloid precursor protein (APP), presenilin 1 (PSEN1), 46 presenilin 2 (PSEN2), apolipoprotein E (ApoE) and a disintegrin and 71 metalloprotease 10 (ADAM10), lead to Alzheimer’s disease." (PMID 33686350, 2021). "This project uses fractal dimension of mRNA and coding DNA sequences (CDS) to probe the lncRNAs within the mRNAs (but not the CDS) in Alzheimer's disease genes, namely, APP or AD1, APOE or AD2, PSEN1 or AD3, and PSEN2 or AD4." (PMID 23662159, 2013).
dementia (46 papers, 2012 to 2025). Loss of intellectual abilities interfering with an individual's social and occupational functions. "In this paper, we will illustrate the mutation spectrum of the PSEN2 gene in the dementia cohort of Peking Union Medical College Hospital (PUMCH)." (PMID 35491795, 2022). "Except in the case of familial AD, some PSEN2 mutations are associated with other disorders, such as dementia with Lewy bodies, frontotemporal dementia, breast cancer, dilated cardiomyopathy and Parkinson’s disease with dementia (PDD)." (PMID 29599933, 2018). "PSEN2 mutation at codon 214 for predicting a valine to leucine substitution was found in a 70-year-old woman, who showed a dementia of the Alzheimer type." (PMID 24885952, 2014). "First, several major YOD risk factors, such as APOE ε4 alleles; APP, PSEN1, and PSEN2 genes; family history of dementia; history of traumatic brain injury; hearing loss; and education level could not be obtained." (PMID 38926887, 2024). "Increasing evidence suggests a role of the PSEN2 p.S130L variant in PD and dementia." (PMID 29692703, 2018). "PSEN2 Val191Glu was observed in a 77-year-old patient with Parkinson’s disease dementia, cognitive decline, and hallucinations." (PMID 39273625, 2024). "PPI network that demonstrated proteins such as PSEN1, PSEN2, APP, MAPT, and C9orf72 had abundant interactions with other proteins, which was consistent with the important roles of these dementia pathogenic genes." (PMID 34720994, 2021). "In this context, it is worth mentioning that several genes linked to dementia, including APP, PSEN1, PSEN2, and ITM2b, play a physiological role in glutamatergic transmission and that mutations linked to familial dementia alter this physiological functions." (PMID 33434745, 2021). "Here, we evaluate BMAA exposure by investigating transcription signatures using PCR for dolphin genes homologous to those implicated in AD and related dementias: APP, PSEN1, PSEN2, MAPT, GRN, TARDBP, and C9orf72." (PMID 34678990, 2021). "Here, we performed a systematic screening of known dementia-causing genes (APP, PSEN1, PSEN2, or GRN genes) in 821 PD cases and 423 controls from North America in addition to 553 PD patients and 550 healthy controls from Spain." (PMID 29692703, 2018). "Recently, PSEN2 p.S130L was reported in an individual with idiopathic PD with dementia (AAO = 73 years)." (PMID 29692703, 2018). "The PSEN2 p.V148I carrier is an early onset PD case (25 years at onset) with a tremor-dominant parkinsonism and positive family history of PD but dementia-free at last assessment after 12 years of PD." (PMID 29692703, 2018). "Autosomal dominant AD (ADAD) is a rare form of AD, caused by mutations in genes encoding presenilin-1 (PSEN1), presenilin-2 (PSEN2), or amyloid precursor protein (APP) and leading to young onset dementia." (PMID 25922840, 2015). "The prevailing pathogenic model for dementias caused by mutations in APP and genes that regulate APP processing (PSEN1, PSEN2 and BRI2/ITM2b) posits that amyloid peptides trigger dementia." (PMID 23217200, 2012). "Mutations in any of 4 genes are causative of early onset dementias due to either AD (presenilin 1 [PSEN1], presenilin 2 [PSEN2], and amyloid precursor protein [APP]) or prion disease (prion protein gene, PRNP)." (PMID 21193246, 2012). "Pathogenic mutations in APP, PSEN1, PSEN2, MAPT and GRN have previously been linked to familial early onset forms of dementia." (PMID 22312439, 2012). "Mutations in the APP, PSEN1, PSEN2, and MAPT genes give rise to well-characterized differential neuropathological and clinical phenotypes of dementia." (PMID 22482072, 2012). "Examining the mutant PSEN2 (N141I (Volga) and M239V) and APP (V717G, V717L, V717I, V717F and A713T) cohorts shows that a large proportion of carriers presented with dementia later than expected for PSEN2, and earlier than expected for APP, based on biochemical AAOs." (PMID 40281586, 2025).
dementia (continued). "There were no genome-wide or suggestive associations with genetic variants in known causal Mendelian dementia genes (APP, PSEN1, PSEN2, and GRN), suggesting that common variants in these genes do not significantly contribute to sporadic EOAD, or that we do not have enough power." (PMID 38883718, 2024). "Patients suffering from familial AD (fAD) develop cognitive impairment and dementia between 50 and 65 years and bear mutations in one of the three genes involved in the β-amyloidogenic pathway: APP, presenilin 1 (PSEN1), and presenilin 2 (PSEN2); increased APP dosage is also causative of AD and CAA." (PMID 39475348, 2024). "Although dementias due to APP/PSEN1/PSEN2 mutations are classified as familial Alzheimer disease (FAD) and those due to mutations in BRI2/ITM2B as British and Danish dementias (FBD, FDD), data suggest that these diseases have a common pathogenesis involving toxic APP metabolites." (PMID 23217200, 2012). "Mutations in these genes confer specific phenotypic profiles to patients with dementia: amyloidogenic pathology associated with APP, PSEN1, and PSEN2 mutations and tauopathy associated with MATP mutations, representing the two major pathogenic hypotheses for AD." (PMID 22482072, 2012). "Our analysis validates the interdependence of AD, dementia, and Parkinson’s disease through various common genes (i.e., A2M, ABCA7, PLAU, PSEN2, and MPO)." (PMID 38790243, 2024). "Given the very rare frequency of APP, PSEN1, and PSEN2 pathogenic mutations detected in the screened patients (two individuals with EOAD), our hypothesis should encourage genetic screening in larger cohorts of both EOAD and LOAD, as well as dementia cases using the gene panel." (PMID 30917570, 2019). "No additional variants were detected in PSEN2, APP, or other dementia causative genes (e.g., MAPT, GRN, and TARDBP)." (PMID 35932032, 2022). "None of these patients had a family history of stroke or dementia, and none had any pathogenic mutation in the APP, PSEN1 and PSEN2 genes to explain early Aβ pathology." (PMID 29450646, 2018). "To investigate this intriguing hypothesis, we analyzed rare coding variability in 6 Mendelian dementia genes (APP, PSEN1, PSEN2, GRN, MAPT, and PRNP), in 141 LOAD patients and 179 elderly controls, neuropathologically proven, from the UK." (PMID 25104557, 2014). "GWASs have shown that common noncoding variability in Mendelian dementia genes (APP, PSEN1, PSEN2, MAPT, GRN, and PRNP) does not influence susceptibility to AD." (PMID 25104557, 2014). "Thus, we screened 6 Mendelian dementia genes (APP, PSEN1, PSEN2, MAPT, GRN, and PRNP) aiming to establish whether rare coding variability in these genes is responsible for an appreciable portion of the LOAD risk." (PMID 25104557, 2014). "In a clinical setting, we recommend to examine an extended panel of dementia genes in familial EOAD, when APP, PSEN1, and PSEN2 are tested negative, as was suggested before." (PMID 35650585, 2022).
familial Alzheimer disease (38 papers, 2006 to 2025). A degenerative disease of the brain that causes gradual loss of memory, judgment, and the ability to function socially. "We also found differential splicing of Presenilin 2 in the Amygdala, one of the most common genes associated with early-onset familial Alzheimer’s disease, with a well-known role in the production of amyloid beta." (PMID 40295477, 2025). "Mutations in the Presenilin genes (PSEN1 and PSEN2) are the major cause of familial Alzheimer’s disease (AD), highlighting the importance of Presenilin (PS) in AD pathogenesis." (PMID 36710361, 2023). "Presenilin-1 (PSEN1) and presenilin-2 (PSEN2) are two genes associated with several diseases, and early studies have focused on their association with familial Alzheimer's disease (FAD), which often leads to early onset of the disease." (PMID 37907783, 2023). "Mutations in the Presenilin genes (PSEN1 and PSEN2) are associated with the major cause of familial Alzheimer’s disease." (PMID 35013145, 2022). "As part of a program analyzing the function of genes involved in familial Alzheimer’s disease, we wished to identify changes in the expression of genes in adult brains due to simple loss of PSEN2 activity." (PMID 32658922, 2020). "At least 15 mutations in the human gene PRESENILIN 2 (PSEN2) have been found to cause familial Alzheimer’s disease (fAD)." (PMID 30359395, 2018). "Presenilin 1 (PS1) and presenilin 2 (PS2), derived from PSEN1 and PSEN2, first identified as genes mutated in families with familial Alzheimer’s disease (FAD), form the catalytic component of the γ-secretase complex." (PMID 24304563, 2014). "Pathogenic mutations in the three known genes – the amyloid precursor protein (APP), presenilin 1 (PSEN1), presenilin 2 (PSEN2) – are known to cause familial Alzheimer's disease (AD) and tend to be associated with early-onset AD." (PMID 25333068, 2014). "The Alzheimer’s Precursor Protein (APP) is also cleaved by γ-secretase, and mutations in the two human presenilin genes encoding PS1 (PSEN1) and PS2 (PSEN2) are responsible for the majority of cases of early-onset familial Alzheimer’s disease (AD)." (PMID 23667524, 2013). "The underlying nature of signaling alterations arising from the mutations in presenilin 1 or presenilin 2 genes that give rise to familial Alzheimer’s disease (FAD) in humans are unclear." (PMID 23720628, 2013). "To date, more than 160 highly penetrant but rare mutations have been described in three genes (amyloid precursor protein, presenilin 1, and presenilin 2) that cause familial Alzheimer's disease." (PMID 24278680, 2012). "Mutations in the genes encoding presenilin 1 (PS1) and presenilin 2 (PS2) cause early-onset familial Alzheimer disease (AD)." (PMID 21206757, 2010). "Mutations in PSEN1 and PSEN2 genes account for the majority of cases of early-onset familial Alzheimer disease." (PMID 16930451, 2006). "Mutations in the PSEN1 and PSEN2 genes are the major cause of familial Alzheimer’s disease." (PMID 33302995, 2020). "Mutations in the presenilin (PSEN) encoding genes (PSEN1 and PSEN2) cause most cases of familial Alzheimer’s disease (AD); however, the underlying mechanism of pathogenesis remains unclear." (PMID 29989545, 2018). "The most extensively investigated include presenilin 1 (PSEN1), presenilin 2 (PSEN2), and amyloid precursor protein (APP) mutations, all of which contribute to elevated Aβ deposition and have been linked to familial Alzheimer’s disease." (PMID 41007636, 2025). "Mutations of three causative genes, namely presenilin 1 (PSEN1), presenilin 2 (PSEN2), and amyloid precursor protein (APP), have been identified as the major causes of early‐onset familial Alzheimer's disease (EOFAD)." (PMID 32767553, 2020). "A major cause underlying familial Alzheimer’s disease (AD) are mutations in presenilin proteins, presenilin 1 (PS1) and presenilin 2 (PS2)." (PMID 29857474, 2018).
familial Alzheimer disease (continued). "There are some inherited forms of the AD, also known as Familial Alzheimer's Disease (FAD), caused by mutations in one of these three genes: Amyloid Precursor Protein (APP), Presenilin-1, and Presenilin-2." (PMID 24669288, 2014). "Early-onset forms of familial Alzheimer's disease (FAD) have been linked to mutations in amyloid precursor protein (APP), presenilin-1 (PS-1), and presenilin-2 (PS-2)." (PMID 22888461, 2012). "Mutations in the presenilin-1 (PSEN1) and presenilin-2 (PSEN2) genes cause early-onset and aggressive forms of familial Alzheimer's disease (FAD)." (PMID 19021905, 2008). "Early-onset, familial Alzheimer’s disease (AD), with a prevalence of around 1%, is known to be associated with high-penetrance mutations in the genes coding for amyloid precursor protein (APP), presenilin 1 (PSEN1), and presenilin 2 (PSEN2)." (PMID 35736408, 2022). "In this study, we investigated the effects of a specific inhibitor of 37/67kDa LR on APP maturation and Aβ generation in fibroblasts from patients affected by familial Alzheimer’s disease (carrying PSEN2 M239V pathogenic mutation, fAD2, fAD3 or not fAD1), compared with healthy unaffected controls." (PMID 33207563, 2020). "Mutations in the human genes PRESENILIN1 (PSEN1), PRESENILIN2 (PSEN2) and AMYLOID BETA A4 PRECURSOR PROTEIN (APP) have been identified in familial Alzheimer’s disease (AD)." (PMID 28636676, 2017).
cognitive decline (15 papers, 2015 to 2025). "Here, we investigate how an AD-linked mutation deregulates expression of circadian genes and induces cognitive decline using the knock-in (KI) mice heterozygous for presenilin 2 N141I mutation." (PMID 35418126, 2022). "Another mutation in PSEN2 (p.V191E) also was found in one late-onset PD patient (AAO = 75 years) with cognitive decline." (PMID 29692703, 2018). "Using fibroblasts isolated from 3 sisters, 2 carrying the PSEN2 mutation and displaying cognitive decline, with the third wild-type for the mutation, iPSCs were developed." (PMID 29078805, 2017). "LOF mechanism is proposed for PSEN1 and PSEN2 mutations in AD, showing that total PSEN1 and PSEN2 LOF in mouse brain caused progressive cognitive decline and neurodegeneration." (PMID 33853652, 2021). "Rare mutations in APP, PSEN1, and PSEN2 cause ADAD; however, the mechanisms by which altered APP processing leads to changes in tau and cognitive decline remain poorly understood." (PMID 30045758, 2018).
frontotemporal dementia (14 papers, 2012 to 2025). Frontotemporal dementia (FTD) comprises a group of neurodegenerative disorders, characterized by progressive changes in behavior, executive dysfunction and language impairment, as a result of degeneration of the medial prefrontal and frontoinsular cortices. "Another study on both AD and frontotemporal dementia (FTD) patients identified three novel mutations in PSEN2." (PMID 32235595, 2020). "Three of these variants have been described in patients with AD, PD or frontotemporal lobar degeneration and amyotrophic lateral sclerosis (Patient A:PSEN2 p.D439A;16, 17 B:CHMP2B p.I29V;18 and C:SQSTM1 p.A33V,19, 20)." (PMID 26836416, 2016). "Some patients with mutations in pesenilin 1 or presenilin 2 (PSEN2) genes are clinically diagnosed with frontotemporal dementia or other neurodegenerative conditions." (PMID 23593396, 2013). "In addition to its association with LOAD, the PSEN2 His169Asn mutation was linked to frontotemporal dementia in this study." (PMID 40149496, 2025). "Mutations in PSEN2 have been reported in association with other diseases, including frontotemporal dementia (FTD), dementia with Lewy bodies (DLB), breast cancer, and dilated cardiomyopathy." (PMID 34456336, 2021). "Interestingly, PSEN2 p.His169Asn mutation was previously identified in one patient with familial LOAD and one patient with sporadic frontotemporal dementia (FTD) from People’s Republic of China; however, the pathogenic nature has not been clarified yet." (PMID 31557888, 2019). "While mutations in APP, PSEN1, and PSEN2 in the Aβ-generation pathway may lead to familial AD showing plaques and tangles, mutations in MAPT may lead to tangle formation but not plaques, resulting in frontotemporal dementia (FTD) or conditions similar to CBD, PSP, or PiD." (PMID 38732197, 2024).
Onset (13 papers, 2011 to 2026). The age group in which disease manifestations appear. "Both the PSEN1 and PSEN2 variants were found in late-onset PD individuals whereas the GRN variant was found in one control." (PMID 29692703, 2018). "Furthermore, mutations in three common genes—amyloid precursor protein (APP), presenilin-1 (PSEN1), and presenilin-2 (PSEN2) are associated with early-onset AD (EOAD), developing in fourth or fifth decade of life." (PMID 33815092, 2021). "However, three early-onset familial AD genes (APP, PSEN1, and PSEN2) and one genetic risk factor for late-onset AD (APOE) have been identified." (PMID 31080696, 2019). "In the majority of familial, early-onset Alzheimer’s, mutations were identified in the genes encoding subunits of the γ-secretase complex – PSEN1 and PSEN2, encoding Presenilin-1 and Presenilin-2, respectively." (PMID 40969213, 2025). "The genes primarily involved in AD are Amyloid Precursor Protein (APP), Presenilin 1 (PSEN1), and Presenilin 2 (PSEN2), which are associated with early-onset familial AD (fAD), variations in apolipoprotein E (APOE) gene increase the risk of late-onset sporadic AD (sAD)." (PMID 39861466, 2025). "Genetic factors also modulate disease risk: the apolipoprotein E (ApoE) ε4 allele is the strongest known genetic susceptibility factor for late-onset AD, whereas mutations in amyloid precursor protein (APP), presenilin-1 (PSEN1), and presenilin-2 (PSEN2) cause rare familial forms of early-onset AD." (PMID 41373799, 2025). "The remaining 2%–5% of cases are early‐onset AD (EOAD) that are linked to genetic mutation(s) in genes involved in amyloid metabolism, such as Amyloid Precursor Protein (APP), Presenilin 1 (PSEN1), and Presenilin 2 (PSEN2)." (PMID 32857910, 2020). "Early-onset AD is a rare hereditary form of the disease that accounts for ~5-10% of all cases and a minority of early-onset cases has been linked to specific mutations in the genes encoding amyloid precursor protein (APP), presenilin 1 (PSEN1), and presenilin 2 (PSEN2)." (PMID 34712240, 2021).